IL1B (interleukin 1 beta)
Diseases named in the same sentence as IL1B in open-access papers (continued):
Sharing a sentence is not in itself a finding about the gene and the disease.
infection (continued). "The resulting iDCs were either infected with HSV-2 strain G or HSV-1 as control, and harvested at 2, 4, 8, or 16 hpi or matured into mDCs, via stimulation with a maturation cocktail, additionally containing IL-1β, IL-6, TNF-α, and PGE2, followed by the same infection procedure as for iDCs." (PMID 31963276, 2020). "As IL-1β production in response to both Mtb infection and LZD treatment depends largely on the NLRP3 inflammasome, we also investigated a regimen in which LZD and a small molecule NLRP3 inhibitor (MCC950) was administered between days 56 and 77 post-infection." (PMID 32477361, 2020). "In reference to the immunomodulatory role of LL-37, P. bovis upregulated mRNA expression of TNF-α, Cxcl-1, and IL-1β in murine phagocytic J774.A1 cells (at 2 and 8 h post-infection), whereas co-stimulation with LL-37 decreased concentrations of TNF-α, Cxcl-1, and IL-1β mRNA expression (p < 0.05)." (PMID 32117805, 2020). "Real-time PCR results show increased mRNA expression of IL-1β by CHME-3 cells infected with both MDR-PA and S-PA strains, while expression was significantly greater in cells infected with MDR-PA at 4, 6, and 12 h post-infection." (PMID 32423093, 2020). "MAP is known to upregulate IL-6, IL-23, IL-1β, and TGF-β mRNA expression as early as 1 h post-infection in MAP-infected MDMs, indicating that the development of Th17 cells may be promoted by the local cytokine environment near sites of MAP infection." (PMID 32258066, 2020). "After 96 h, 2 and 10 weeks of infection lung leukocytes were obtained from infected AhR−/− and WT mice and analyzed by flow cytometry for the presence of intracellular cytokines (IL-12, TNF-α, IL-1β, IL-6, TGF-β and IL-10) in CD11c+ gated cells." (PMID 32647342, 2020). "While its role during infection with enteric Yersinia species in vivo is yet to be defined, mouse NLRP12, whose activation mechanisms remain poorly understood, also contributes to IL‐1β release from bone marrow‐derived macrophages infected with Y. pseudotuberculosis or Y. enterocolitica." (PMID 32185892, 2020). "In addition, infection of C57BL/6 mice with L. major leads to enhanced release of the TH1-inducing cytokines IL-12, IL-1β and TNF in the infected skin." (PMID 33584721, 2020). "In further support of a more active or efficient phagosome rupture induced by M. tuberculosis isolate 4I2, chemical inhibition of K + channels or of cathepsin B decreased the secretion of IL-1β by 4I2-infected macrophages, while not affecting 6C4 infections." (PMID 32327653, 2020). "Contrary to the LPS/ATP-treated positive control, infection with Ab-opsonized or non-opsonized parasites does not result in IL-1β secretion (Figure 2A1), demonstrating the absence of inflammasome activation as we observed previously in macrophages." (PMID 32582184, 2020). "While an early activation of interferon α/β signaling was observed, several innate immune signaling pathways including TLR, TNF, NF-κB, and NOD-like receptor signaling and key inflammatory cytokines such as Il-1α, Il-1β, and TNF typically activated following infection were suppressed." (PMID 32722194, 2020). "It is also interesting to note that in vitro infection of mouse macrophages and human monocytes with T. gondii only leads to the secretion of IL-1β, but not IL-1824,52." (PMID 32753607, 2020). "The results showed that treatment with anti-IL-1β neutralizing antibody decreased body temperature compared to that after treatment with negative serum or PBS after GM infection." (PMID 32293543, 2020). "Infection with strain 89-1591 failed to induce a robust IL-1β response in plasma, regardless of time, with values lower than 25 pg/mL." (PMID 32098284, 2020). "The basic inflammasome response was not drastically changed in these cells upon infection with H. pylori, but Nigericin treatment significantly increased the secretion of mature IL-1β." (PMID 32230726, 2020).
infection (continued). "In lung tissues, the TNF-α, IL-1β and IL-6 levels in the positive control group were all significantly higher compared with the negative control group at 72 h after infection." (PMID 33551807, 2020). "In contrast with control animals, mice with pulmonary TB showed a significant decrease in NE, DA, EP and 5-HT in the hypothalamus and cerebellum from day one of infection, when in this model there is a high production of pro-inflammatory cytokines in the lungs, such as TNF-α and IL-1-β." (PMID 33322180, 2020). "In contrast, infection of murine DCs with a mutant lacking CagPAI resulted in reduced levels of IL-1β after overnight treatment." (PMID 32486097, 2020). "In the absence of Th1 signature cytokines, such as TNF-α, IFN-γ, IL-1β and IL-12, infected mice succumb to infection." (PMID 32517114, 2020). "Various inflammatory cytokines (IL-1β, IL-6, IL-12, TNF-α) are increased inleptospirosis as an immune response to the infection, however, this increase may behigher in severe stages of the disease." (PMID 32578717, 2020). "For teleosts, which rely on non-specific immune processes to enhance their immune response and resist pathogen infection, cytokines such as TNF-α, IL-1β, IL-6, IL-10, IL-12, and TGF-β, primarily produced by activated macrophages, also play an important role in the immune system." (PMID 32457762, 2020). "However, 5 days after infection (day 5), the levels of IL-6, TNF-α, and IL-1β in group ZE were significantly lower than the model group." (PMID 32486242, 2020). "To address this, we infected mice lacking either IL-1α or IL-1β and analyzed the cellular immune response and parasite burden during chronic phase of infection." (PMID 32703941, 2020). "This is consistent with a recent study by Sommer and Fabri, suggesting that VitD3 increases IL-1β to prime the innate response by influencing IL-1β gene transcription as no IL-1β is released prior to infection." (PMID 32318074, 2020). "MCC950 has additionally been demonstrated to decrease IL-1β secretion upon monocyte infection with T. gondii; however, there is an absence of research pertaining to this inhibitor in in vivo chronic infection models." (PMID 32711529, 2020). "Both hantavirus species failed to induce NF-kB driven transcripts, such as IL-6 and IL-1β within 48 h of infection." (PMID 32596167, 2020). "This fits the clinical picture in which increased values of IL-1β are detected together with TNFα in chronic low-grade peri-implant inflammation without any sign of infection." (PMID 33343230, 2020). "The release of TGF-β1-transporting vesicles was seen in wild-type mouse blood in early infection with no significant upregulation of IL1b transcription." (PMID 32393780, 2020). "We infected immortalised wild-type murine bone marrow-derived macrophages (iBMDMs) using a panel of clinical isolates from the Euro-American and Beijing lineages as well as the H37Rv reference strain, followed by immunoblotting and ELISA for IL-1β and TNF at 24 h post-infection." (PMID 32111888, 2020). "Since studies had reported that NH/P68 induced enhanced cytokine gene expression or production in macrophages compared to a virulent isolate, cytokine gene (IL-1β, IL-6, IL-10, IL-12p40, IL-18, TNF-α) expression in moMΦ after NH/68 or 22653/14 infection were monitored over-time." (PMID 32178332, 2020). "The analysis of the mRNA profiles showed that, while C3 and cxcr4a mRNA levels did not change throughout the experiment, ccr6a, akr2, and IL-1β levels increased after vaccination with α-Gal and remained unchanged after infection." (PMID 32344637, 2020). "Upon VACV strain infection, the HD11 cells produced IFNβ, OASL, IL-1β, and IL-8 transcripts." (PMID 32660114, 2020). "In addition, I3C treatment reduced the inflammatory response to Cr infection by maintaining anti-inflammatory cytokine IL-22 mRNA levels while reducing expression of other pro-inflammatory cytokines including IL17A, IL6, IL1β, TNF-α, and IFN-γ." (PMID 33076301, 2020).
infection (continued). "In addition, treatment of macrophages with 2-DG or the use of glucose-deprived media impaired the production of proinflammatory cytokines, including IL-1β, TNF, and IL-6, after 24 h of infection." (PMID 32385235, 2020). "Since CXCL-8, IL-1β and TNF-α resulted as statistically significant overexpressed cytokines after 2h post infection, we analyzed their concentration at a protein level in supernatants of neutrophils infected with A. baumannii ATCC® 19606TM also 4 h after infection." (PMID 33253325, 2020). "Upon infection with K. pneumoniae strain A54970, no IL-1β production was induced in infected macrophages, suggesting a lack of inflammasome activation and associated pyroptosis." (PMID 32425944, 2020). "For example, experimental infection with L. major resulted in nonhealing cutaneous lesions being this fact related to increased IL-1β production via NLRP3 inflammasome and local neutrophil recruitment." (PMID 31961876, 2020). "Differential IL-1β induction was observed upon infection of PBMCs from IGRA+ or IGRA– donors, and upon infection of purified monocytes from IGRA– individuals, macrophages differentiated from the human monocytic cell line THP-1 or mouse bone marrow-derived macrophages (BMDMs)." (PMID 32327653, 2020). "We found that the IFN-α formulation could reduce the expression of IL-1β and COX-2, which were upregulated by infection with fimA types A and B P. gulae strains." (PMID 32080231, 2020). "Notably, in agreement with the highest level of F. columnare in the BM, the significantly upregulated mRNA expression of immune-related genes (e.g., CATH-2, HP1, IL-8, IL-1β, and RIG1) was detected at days 1, 2, 4, and 7 post-infection." (PMID 33072100, 2020). "Thus, TF expression is induced both in normal cells (mostly vascular or fibroblastic-type cells and monocytes after injury or infection) and in tumor cells by a variety of inflammatory and growth factors including VEGF, TNFα, IL-1β, IL-6, or IL-8." (PMID 32152404, 2020). "Infection with C. albicans led to early upregulation of all factors analyzed in WLA blood, with the exception of IL-1β and IL-6, which were not induced by infection." (PMID 32296424, 2020). "The cells were then mock infected with fresh media, infected with green fluorescent protein (GFP)-expressing type II (Prugniaud strain) T. gondii at a multiplicity of infection (MOI) of 1 or 2, or treated with interleukin-1beta (IL-1β) as a positive control to induce barrier permeability." (PMID 31996420, 2020). "In general, IL-1β induces the production of chemoattractants, such as CXCL1 and CXCL2 by lung epithelial cells, which enhance neutrophil influx and subsequent bacterial clearance at the site of infection." (PMID 33424869, 2020). "As we previously demonstrated, Fn U112 infection of NLRP3 inflammasome-reconstituted HEK293T cells elicited robust IL-1β production and cells lacking NLRP3, or expressing NLRP2, yielded IL-1β levels comparable to uninfected controls." (PMID 32983094, 2020). "Interestingly, in CD-derived MoDC, the ratio between the amount of IL-1β, IL-23 and IL-10 and the number of intracellular LF82 cells after 24 h of infection was significantly higher compared to HD-derived MoDC, while IL-12 levels were significantly lower." (PMID 32752244, 2020). "In contrast, transcripts for other cytokines known to be secreted during DC maturation (tnf, il6) and after inflammasome activation (il1β, il18) were down modulated during infection, in accordance to the absence of secretion of these cytokines." (PMID 32582184, 2020). "Absence of IFNAR further increased IL-1β secreted by BMDMs infected with isolate 4I2, but did not impact IL-1β secretion upon infection with 6C4." (PMID 32327653, 2020).
infection (continued). "Enhanced expression of acute and chronic cytokines, such as IL-1β, TNF-α, and MIP-1α was also detected, especially in the lung (the initial infection site), and spleen (a representative tissue of systemic immunity) of the transgenic mice following challenge with MERS-CoV." (PMID 31838832, 2020). "Thus, we examined the expression of IL-1β, IL-6, IL-8, and TNF-α in primary porcine alveolar macrophages (PAMs) during infection." (PMID 31363150, 2019). "IFN-γ, IL-1β, and TNF-α are important cytokines related to infection and immunity." (PMID 32038632, 2019). "Strikingly, while L.g.− -derived EVs did not affect IL-1β production upon infection by both clones, L.g.+-derived EVs rescued L.g.− capacity to impair inflammasome activation in WT macrophages in a TLR3-dependent manner." (PMID 31754185, 2019). "In agreement with the experiments using the P2X7 inhibitor, B6 and P2X7−/− BMDMs released comparable levels of IL-1β after infection with the wt strain, while nga(G330D) bacteria induced increased IL-1β secretion from B6 but not from P2X7−/− BMDMs." (PMID 31275321, 2019). "Noticeably, PC1 mostly segregated the non-infected vs. infected populations and PC2 distinguished the infection parameters (infection index, percentage of infection, oxidative burst, Elastase, and MPO) vs. the cytokines IL-6, IL-10, IL1-β, and TNF-α production." (PMID 31134162, 2019). "Similarly, treatment of bMDM with IL10 siRNA enhanced expression of IL1B, TNF, IL6, IFNG and NOS2 induced by G18 infection." (PMID 31527895, 2019). "IL1β and TNF-α regulate inflammatory responses in a variety of diseases and infections." (PMID 31002726, 2019). "TNF-α (A) and IL-1β (B) plasmatic levels were determined in control non-infected and infected mice after the infection (5–40 days) by ELISA." (PMID 31138231, 2019). "Co-colonization of ASF-associated mice with SFB induced higher expression of pro-inflammatory cytokines such as Tnfα, Il1β, and Il12a upon MNV infection compared to infected ASF-associated mice without SFB." (PMID 31396223, 2019). "By stabilizing Hif-1α, macrophage Il-1β can be primed in the absence of infection and is protective upon M. marinum infection via neutrophil NO production." (PMID 30552162, 2019). "While P2X7 inhibition did not affect IL-1β release from BMDMs infected with wt bacteria, the IL-1β released upon nga(G330D)-infection was dose-dependently reduced, plateauing at levels similar to those induced by wt bacteria." (PMID 31275321, 2019). "Blood TNF-α and IL-1β levels did not change during the course of infection, which suggests that systemic inflammation does not explain the neuroinflammatory events observed in the spinal cord." (PMID 31138231, 2019). "In contrast to the effect of IL10 knock-down during G18 infection of bMDM, IL1B and IL6 mRNA levels were not significantly affected by IL10 knock-down during AF2122/97 infection." (PMID 31527895, 2019). "Here, restriction of dietary Zn intake resulted in only an increase in the activation of IL-1β and IL-6, but without infection resulting in a generalised dysregulation of inflammatory responses." (PMID 31437249, 2019). "Lower IL‐1β and IL‐18 levels in RH‐CHIKV infection may lead to dampened NLRP3 pathways, resulting in reduced joint inflammation during acute phase of infection." (PMID 31015278, 2019). "Production of IL-1β was almost completely abrogated in the absence of MyD88 following infection with both S. suis strains (p < 0.01)." (PMID 31262357, 2019). "Amongst cytokines, the genes for Cxcl9, Cxcl10, Cxcl13, Il-1β, Il-6, Tnf, Tnfsf10, IFN-γ, Ccl2, Ccl4, Ccl7, Ccl17, and Mif were highly up-regulated (ranging from 2- to 405-fold, p ≤ 0.05), whereas Cxcl12 and Cxcl14 were down-regulated during in vivo infection." (PMID 30857242, 2019).
infection (continued). "Therefore, using qPCR, we determined the expression of a variety of cytokines with neutrophil chemotactic properties including IL-6, CCL3, CXCL2 and G-CSF, as well as pro-inflammatory cytokines IL-1β and TNF-α at day 3 (105 PFUs) post-infection." (PMID 30787331, 2019). "The link between HIF-1α and IL-1β has been previously demonstrated in murine macrophages via inflammatory activation by succinate, in the absence of infection." (PMID 30552162, 2019). "IL-1β, TNFα, IL-6 and IFNγ were not significantly elevated during relapses compared to pre-infection values, and Monokine Induced by Interferon Gamma (MIG) was the only cytokine significantly increased during relapses." (PMID 31536608, 2019). "Despite this, cytochalasin did not reduce MDM supernatant TNF, IL-6, and IL-1β (not shown) responses to infection with either the TIGR4 or the TIGR4 Δcps strain, with most responses actually showing non-statistically significant increases." (PMID 31551336, 2019). "All these data suggest that, at least for some infections such as CP, any perturbation to the delicate balance between inflammasome activation and IL-1β secretion can have negative results." (PMID 31031755, 2019). "Deficiency of IFNAR resulted in attenuation of caspase-11 mediated-noncanonical inflammasome activation during IOE infection, also leading to reduced secretion of IL-1β and minimal cell death." (PMID 31134081, 2019). "In mice, IL-1β is critical for the resistance against experimental GBS and S. aureus infection, likely via IL-1R-mediated chemokine production which recruits neutrophils to the site of infection." (PMID 31214180, 2019). "However, infection with Salmonella typhimurium, activator of the NLRC4 inflammasome, led to caspase-1 activation and increased IL-1β production in BMDMs from Lgal3−/− mice." (PMID 31406212, 2019). "Similarly, infection of human corneal epithelial cells with virulent HSV-1 clinical isolate KOS79 induced a significant early activation of Caspase-1, IL-1β and IL-18." (PMID 31367214, 2019). "Moreover, during early infection, PRRSV-2 has been reported to induce both IL1β mRNA expression and secretion in a time- and dose-dependent manner, as mediated by the TLR4/MyD88 pathway and by the NLRP3 pathway." (PMID 30862035, 2019). "At 1 week after infection, several cytokines responsible for immune cell recruitment were significantly up-regulated in infected-only control defects, including G-CSF, MIP-1α, MIP-1β, MIP-2, KC, IP-10, IL-6, and IL-1β." (PMID 31114804, 2019). "AdV alone did not induce Il1b, Tnf or Ifnb mRNA expression at 3 h post‐infection, but AdV in the presence of WT h9C12 induced their expression approximately 10‐fold." (PMID 31468569, 2019). "Albeit not statistically significant, the levels of G-CSF, IL-1α, MCP-1/CCL2, MIP-2/CXCL2 at day 1, G-CSF, KC, MCP-1, and MIP-2 at day 2, and IL-1α, IL-1β, IL-6, IL-10, MCP-1, MIP-2, and TNF at day 3 post-infection were 1.5–4.4-fold higher in SIRT3/5−/− than in SIRT3/5+/+ mice." (PMID 31632409, 2019). "NK cells stimulated by IL-12 or IL-18, secreted from dendritic cells and macrophages, produce several cytokines, principally IFN-γ, IL-1β, IL-8, IL-17A, and tumor necrosis factor alpha (TNF-α), which are involved in lung inflammatory processes and infection resistance." (PMID 31269777, 2019). "In the absence of infection, senescent cells show increased, low-grade, basal systemic inflammation (characterized by higher levels of IL-1β, IL-6, and tumor necrosis factor-α), which is known as inflammaging." (PMID 30940096, 2019). "To investigate whether ERS contributed to the production of IL-1β during M. bovis infection, we pretreated BMDMs with the chaperone 4-PBA, an ERS inhibitor, followed by infection with M. bovis." (PMID 30846986, 2019). "Both hydroxylase inhibitors increased il-1β:GFP in the absence of infection to a similar extent as that observed with DA Hif-1α." (PMID 30552162, 2019).